TFF1 (trefoil factor 1)
Diseases named in the same sentence as TFF1 in open-access papers (continued):
Sharing a sentence is not in itself a finding about the gene and the disease.
gastric cancer (continued). "The expression of TFF1 is frequently down-regulated in human gastric cancer whereas its knockout leads to the development of gastric adenomas and carcinomas in mouse models." (PMID 25015107, 2014). "Previous studies have shown that TFF1 inhibits growth and promotes apoptosis in gastric cancer cells." (PMID 25015107, 2014). "Previous studies have demonstrated that expression of gastrokine-2 inhibits the proliferation of gastric cancer cells and the progression of gastric cancer in vivo, in a trefoil factor 1-dependent manner." (PMID 25270871, 2014). "DNA and histone methylation, and promoter methylation of the TFF1 gene have also been observed in human gastric cancer." (PMID 24216700, 2013). "To study the influence of the cuprocomplex TFF1-Cu on H. pylori colonisation, we used an inducible clone of the gastric carcinoma cell line AGS able to hyper-express TFF1, AGS-AC1 cells." (PMID 24236136, 2013). "However, the occurrence of gastric cancer is commonly accompanied by an increased level of cyclooxygenase-2 (COX2) and a decrease in mucous-associated protein trefoil factor 1 (TFF1), a tumor suppressor." (PMID 35902872, 2022). "Totally, all these results highlighted the clinical significance of TFFs in gastric cancer and support the idea that TFF1 and TFF2 could be the potential biomarkers for the gastric cancer diagnosis and prognosis." (PMID 36428568, 2022). "To determine the clinical relevance of the key down-regulated genes in the gastric cancer cohort, we performed a Kaplan–Meier survival analysis and observed that patients with lower TFF1 and TFF2 levels owned shorter overall survival (OS) and tumor-free survival (TFS) time." (PMID 36428568, 2022). "Moreover, some studies indicated that TFF1 played an important role in the interacting of H. pylori and epithelial cells and related to gastric cancer." (PMID 36157217, 2022). "In gastric cancer cells, miR-423-5p regulates cell proliferation and invasion by targeting trefoil factor 1, and in hepatocellular carcinoma, miR-423-3p overexpression promotes cell growth and regulates G1/S transition by targeting p21Cip/WaF1, a tumor suppressor gene." (PMID 35008806, 2021). "In human gastric cancer, TFF1 has been found to decrease, and it has been proposed that it might act as a tumor suppressor factor." (PMID 34679875, 2021). "Indeed, a recent study demonstrated that the overexpression of TFF1 inhibits EMT through regulation of TGF-β in gastric cancer cells." (PMID 34679875, 2021). "MiRNA‐423‐5p participates in gastric cancer (GC) cell invasion by downregulating TFF1 expression." (PMID 33174687, 2020). "Deletion of Trefoil factor 1 (TFF1) protein promotes β‐catenin activation and gastric tumorigenesis, while miR‐423‐5p expression targets negative regulation TFF1 expression and participated in proliferation and metastasis‐related processes of gastric cancer cells." (PMID 33174687, 2020). "Tanaka Tomokazu and colleagues found that low expression of Trefoil factor 1 (TFF1) was relevant to poor survival in gastric cancer patients who were treated by surgery alone, while the expression of TFF1 was silenced by DNA methylation and was also associated with tumor invasion." (PMID 32489454, 2020). "Based on our findings, it is plausible to suggest that TFF1 is a major anti-inflammatory peptide that may have potent, suppressive effects against inflammation-driven development and progression of gastric cancer." (PMID 31292446, 2019).
gastric cancer (continued). "The reconstitution of TFF1 levels in TFF1-KO gastric gland organoids and human gastric cancer cells, significantly decreased the phosphorylation and nuclear localization of STAT3 with reduced expression of several known STAT3 target genes, further establishing a link between TFF1 and STAT3." (PMID 31292446, 2019). "To ascertain that the accumulation of tumor-associated macrophages was a common occurrence for intestinal-type gastric cancers, we assessed macrophages density in the submucosa and mucosa of tumor-bearing gp130FF and Tg(Tff1-CreERT2); Pik3caH1047R/+; Ptenfl/fl mice." (PMID 31227713, 2019). "A recent study has shown that PIEZO1 regulates epithelial restitution and cell mobility in gastric cancer cells through interaction with trefoil factor family 1 (TFF1), a member of the TFF-domain peptide family; and knockdown of PIEZO1 expression reduces cell migration in gastric cancer cell lines." (PMID 30745454, 2019). "We therefore hypothesized that the downregulation of GATA6 could lead to the downregulation of TFF1/2 in gastric cancer." (PMID 27598141, 2016). "Previous studies have demonstrated that TFF1/2 are downregulated in gastric cancer, which suggests that they may be tumor suppressors." (PMID 27598141, 2016). "Moreover, animals with TFF1 inactivation developed gastric pre-malignant lesions and gastric cancer." (PMID 26417932, 2015). "This study has shown that a combination of reduced TFF1 expression and high TFF3 expression (p = 0.018) was determined as an independent prognostic factor significantly associated with poor OS in patients with early stage gastric cancer." (PMID 25980439, 2015). "In addition to inhibition of cell growth, we next examined the role of TFF1 in inducing apoptosis in gastric cancer cells." (PMID 25015107, 2014). "Furthermore, using a tumor xenograft mouse model of gastric cancer, we demonstrated that reconstitution of TFF1 suppresses tumor growth in vivo." (PMID 25015107, 2014). "Further statistical analysis revealed that the mean serum TFF1 level in gastric cancer was significantly higher than those in both CNAG (P = 0.0075) and healthy group (P = 0.0045) patients, however, it was not significantly different from that in CAG (P = 0.1332)." (PMID 24720760, 2014). "To determine whether TFF1 suppresses growth in gastric cancer cells, we generated two gastric cancer cell lines, AGS and STKM2, stably overexpressing TFF1 or control empty vector pcDNA, and performed colony formation assay." (PMID 25015107, 2014). "A large body of TFF1 literature has suggested TFF1 as a tumor suppressor gene in gastric cancer." (PMID 25015107, 2014). "While there are evidences showing that TFF1 suppresses growth and induces apoptosis in gastric cancer cells, one study has shown that recombinant TFF1 could have anti-proliferative and anti-apoptotic effects in gastrointestinal cells." (PMID 25015107, 2014). "Thus, gastric cancer samples had significantly lower TFF1 immunoreactivity than normal gastric mucosa, consistent with previous reports (P for chi-square = 0.007)." (PMID 21635755, 2011). "In addition, the TFF1 gene in close proximity to the retroelement was undermethylated in gastric cancers." (PMID 21092120, 2010). "The patterns of expression of TFIZ1 and TFF1 in gastric cancer are also examined as this could shed light on the contribution of TFIZ1 to the tumour suppressor activity of TFF1." (PMID 18722547, 2009). "In contrast, TFF1 is sometimes expressed in the absence of TFIZ1 in gastric cancer cells and this expression is associated with metastasis (lymph node involvement: p = 0.007)." (PMID 18722547, 2009). "The dissociation of TFF1 and TFIZ1 protein expression in gastric carcinoma cells could provide an explanation for the apparent contradiction that TFF1 expression is beneficial in normal tissue but detrimental in cancerous tissue (May and Westley, 1997)." (PMID 18722547, 2009).
gastric cancer (continued). "For example, the overexpression of TFF1 suppressed nuclear factor kappa-light-chain-enhancer of activated B-cells (NF-kB) signaling and, therefore, pro-tumorigenic and metastatic properties in colon and gastric cancer cells as well as ß-catenin signaling in hepatocellular carcinoma cells." (PMID 39410561, 2024). "TFF1 is a well-known tumor suppressor in gastric cancer (GC) and a downstream target of the nuclear receptor estrogen-related receptor gamma." (PMID 36917092, 2023). "Specifically, we evaluated the effect of some pro-inflammatory cytokines on TFF1 regulation in GC and primary gastric cells by RT-qPCR and luciferase reporter assay analyses and the repressor role of the transcription factor C/EBPβ, overexpressed in gastric-intestinal cancer." (PMID 36514982, 2022). "Therefore, we considered that TFF1/TFF2 might be the potential DNA methylation target for gastric cancer." (PMID 36428568, 2022). "In human gastric cancer, there are two probable causes for the low expression or absence of TFF1: 1) potential genetic alterations, including gene mutation, loss of heterozygosity (LOH), and DNA methylation; 2) poorly differentiated cells and glands, which are extremely altered to secrete TFF1." (PMID 34679875, 2021). "Given the higher expression of TFF1 in circulating neoplastic cells, we speculate that TFF1 can be detected in the serum, and, therefore, might be applicable in clinical practice as a non-invasive biomarker for the screening of gastric cancer progression." (PMID 34679875, 2021). "Moreover, GKN1, GKN2, and TFF1 expressed in stomach pit-like cells were thought to be gastric tumor suppressor genes, and since mouse TFF1 knockout could induce gastric cancer, these findings support the anti-tumor effect of these genes." (PMID 35141228, 2021). "The fact that TFF1 is silenced in the majority of human gastric cancers by genetic, epigenetic, and transcription mechanisms highlights the importance of our results and denotes a previously unknown protective function of TFF1 against the oncogenic activation of STAT3 in gastric cancer." (PMID 31292446, 2019). "In contrast, gastric cancer usually displays reduced TFF1 expression levels and TFF1-knockout mice are prone to develop gastric carcinomas, consistent with the notion that the downregulation of TFF1 may play an important role in the development of this cancer type." (PMID 29296124, 2017). "Since the studies that focused on TFF1 deregulation in gastric cancer did not consider these molecular subgroups, it is difficult to establish whether TFF1 loss would be a common feature in this cancer type or subgroup-specific." (PMID 29296124, 2017). "The suppression of GATA6 may further downregulate TFF1/2 in gastric cancer." (PMID 27598141, 2016). "Furthermore, TFF1 has been shown to be markedly down-regulated in human gastric cancer." (PMID 24720760, 2014). "Among these DEGs, we observed that two components of the TFF family (TFF1 and TFF2) were mostly downregulated in gastric cancer cases." (PMID 36428568, 2022). "This suggests that TFF1 and TFF2 play important roles in gastric cancer tumorigenesis and progression." (PMID 36428568, 2022). "Taken together, our findings suggested that TFF1 and TFF2 were both downregulated in gastric cancer, and their mRNA expressions were silenced by DNA methylation." (PMID 36428568, 2022). "Heterodimeric interaction between TFF1 and GKN2 has been reported to entail synergistic anti-proliferative and pro-apoptotic effects on gastric cancer cells." (PMID 31963721, 2020). "Given the fact that TFF1 is a secreted protein, AGS gastric cancer cell lines were treated with TFF1 recombinant protein (400 ng mL−1) for 24 h, followed by stimulation with IL6 (100 ng mL−1) for 30 min." (PMID 31292446, 2019). "Using IHC on gastric cancer tissue microarrays, we evaluated the protein expression of TFF1 and STAT3 in human gastric cancer and normal tissue samples." (PMID 31292446, 2019).
gastric cancer (continued). "Therefore, we further confirmed this point in SGC-7901 gastric cancer cells and obtained the same conclusions, which indicated that the low protein levels of c-myc (column 2 of lane 4) and high protein levels of TFF1 (column 2 of lane 5) when C/EBPα was overexpression." (PMID 30644437, 2019). "The AUC for HP positive gastric cancer patients were significantly larger for TFF3 (0.83, 95% CI [0.73, 0.94]) and PG I/II ratio (0.86, 95% CI [0.74, 0.98]) than those for either TFF1 or TFF2." (PMID 24720760, 2014). "The serum concentrations of TFF1, TFF2, and TFF3 in the control groups were significantly lower than those in the gastric cancer group with the exception of TFF2 which was elevated in CAG." (PMID 24720760, 2014). "In Helicobacter-infected human or mouse tissues, TFF1 was moderately epigenetically repressed, but much greater TFF2 repression was observed in stomach cancer." (PMID 24216700, 2013). "Both TFF1 and TFF2 expression are frequently lost in gastric cancer and aberrant promoter methylation has been suggested to be an important mechanism." (PMID 23217022, 2012). "The top 10 marker genes shown here, such as TFF1 and PGC, are correlated to the gastric mucosal barrier and cellular protection, and the expression of TFF1 was indicated to be reduced in some gastric cancer patients, particularly in some precancerous lesions, such as atypical hyperplasia." (PMID 39044041, 2024). "The Trefoil factor 1 (Tff1) gene regulatory elements of the Tff1:CreERT2 BAC-transgenic construct confers expression to foveolar epithelial surface cells of the gastric mucosa as the site of gastric cancer development." (PMID 37957015, 2024). "For example, TFF1 promoted anchorage-independent growth in colon carcinoma cells, phosphoinositide 3-kinases (PI3K) dependent migration and invasion in gastric carcinoma cells, and cyclooxygenase-2 (COX-2) and EGF receptor (EGFR)-dependent angiogenesis in kidney and colonic cancer cells." (PMID 39410561, 2024). "Totally, we considered that TFF1 and TFF2 could be the potential DNA methylation biomarkers for gastric cancer." (PMID 36428568, 2022). "Although it has been shown that TFF1 and TFF2 are downregulated in primary gastric cancer, the interaction between TFFs and DNA methylation in gastric cancer remains unknown." (PMID 36428568, 2022). "Therefore, we explored if TFF1 interferes with the formation and activation of the IL6–IL6Rα–GP130 complex in gastric cancer." (PMID 31292446, 2019). "Importantly, treatment with 2.5 μm of RHD6 restored the expression of GATA6 and TFF1/2 in AGS, MKN28, and MKN45 gastric cancer cells." (PMID 27598141, 2016). "In addition, by exploiting genetic engineering, a variety of transgenic and knockout mouse models of gastric cancer have emerged, such as INS-GAS mice and TFF1 knockout mice." (PMID 24216700, 2013). "This indicates that TFF1 expression in the absence of TFIZ1 expression has potentially deleterious consequences in gastric cancer." (PMID 18722547, 2009). "Totally, TFF1 and TFF2 could be the potential DNA methylation biomarkers for gastric cancer." (PMID 36428568, 2022). "In addition, using the gain of function assay, it was found out that TFF1 and TFF2 could suppress the pathogenesis of gastric cancer." (PMID 36428568, 2022). "Based on these results, we suspected that TFF1/TFF2 could potentially act as the putative tumor suppressor in GC, and these two TFFs were of great value for predicting the overall survival (OS) status in the gastric cancer cohort." (PMID 36428568, 2022). "We reported that serum TFF1, TFF2, and TFF3 could be good biomarkers for gastric cancer screening." (PMID 28687783, 2017). "Thus, TFF1 and TFF2 (TFF1/2) are frequently downregulated in gastric cancer." (PMID 27598141, 2016).
gastric cancer (continued). "In the current study, gastric cancer cells were then treated with rhodium(III) complex 6 (RHD6), a novel STAT3 inhibitor, to determine whether the suppression of STAT3 would derepress GATA6 and TFF1/2." (PMID 27598141, 2016). "TFF1 plays a negative role in regulating H. pylori-mediated activation of NF-κB and STAT3 in gastric cancer cells." (PMID 34419066, 2021). "A number of other genetic alterations have been reported in gastric cancer, including CDH1, β-catenin, TFF1, and Met, but no study compared these alterations by anatomic subsite." (PMID 23717493, 2013).